YJU2 (YJU2 splicing factor homolog)
Description:
Part of the spliceosome which catalyzes two sequential transesterification reactions, first the excision of the non-coding intron from pre-mRNA and then the ligation of the coding exons to form the mature mRNA. Plays a role in stabilizing the structure of the spliceosome catalytic core and docking of the branch helix into the active site, producing 5'-exon and lariat intron-3'-intermediates (By similarity).
Synonyms: CCDC94; FLJ10374
Tractability: Small molecule: a structure with a bound ligand is known. PROTAC: ubiquitination databases record sites on it.
Gene: Protein-coding gene on chromosome 19 (4,247,080 to 4,269,091, forward strand). Ensembl gene ENSG00000105248.
Subcellular location: Nucleus
Subcellular location (Human Protein Atlas): Nucleoplasm
Pathways (Reactome):
Metabolism of RNA: mRNA Splicing - Major Pathway
Gene Ontology:
Molecular function: protein binding
Biological process: mRNA cis splicing, via spliceosome; mRNA splicing, via spliceosome; generation of catalytic spliceosome for first transesterification step
Cellular component: nucleus; spliceosomal complex; U2-type catalytic step 1 spliceosome; nucleoplasm
Genetic constraint (gnomAD): Loss-of-function variants: 28 observed, 36.5 expected, observed/expected ratio (o/e) 0.77, 90% interval 0.57 to 1.05. The upper end of that interval is the gene's LOEUF score, 1.05, which puts it in group 4 of 6, group 1 being the genes least tolerant of losing a copy. Missense variants: 324 observed, 430.84 expected, observed/expected ratio (o/e) 0.75, 90% interval 0.69 to 0.82. Synonymous variants: 183 observed, 183.07 expected, observed/expected ratio (o/e) 1, 90% interval 0.88 to 1.13.
Homologues: Orthologues: chimpanzee YJU2 (99% identical), dog YJU2 (85% identical), pig YJU2 (85% identical), rat Yju2 (80% identical), mouse Yju2 (80% identical), rat Yju2l1 (80% identical), macaque YJU2 (79% identical), guinea pig YJU2 (74% identical), zebrafish yju2 (67% identical), tropical clawed frog yju2 (67% identical), Drosophila melanogaster CG8435 (52% identical), Caenorhabditis elegans yju-2 (39% identical). Paralogues in human: YJU2B (29% identical).
Diseases named in the same sentence as YJU2 in open-access papers:
YJU2 is named in the same sentence as 1 disease in open-access papers, as found by Europe PMC text mining. Sharing a sentence is not in itself a finding about the gene and the disease.
YJU2 shares sentences with these, for which no sentence is quoted: cancer (1 paper).